CFAP276 (cilia and flagella associated protein 276)
Description:
Microtubule inner protein (MIP) part of the dynein-decorated doublet microtubules (DMTs) in cilia axoneme, which is required for motile cilia beating. May play an important role for the maintenance of myelin-axon integrity (By similarity). May affect intracellular Ca(2+) homeostasis.
Synonyms: C1orf194; C10orf194
Tractability: Small molecule: a structure with a bound ligand is known.
Gene: Protein-coding gene on chromosome 1 (109,105,951 to 109,113,857, reverse strand). Ensembl gene ENSG00000179902.
Subcellular location: Cytoplasm; Cytoplasm, cytoskeleton, flagellum axoneme; Cytoplasm, cytoskeleton; Cytoplasm, cytoskeleton, cilium axoneme
Subcellular location (Human Protein Atlas): End piece; Mid piece; Principal piece
Gene Ontology:
Biological process: flagellated sperm motility
Cellular component: axonemal microtubule; cytoplasm; cytoskeleton; axonemal B tubule inner sheath; sperm flagellum; axoneme
Genetic constraint (gnomAD): Loss-of-function variants: 23 observed, 21.79 expected, observed/expected ratio (o/e) 1.06, 90% interval 0.76 to 1.49. The upper end of that interval is the gene's LOEUF score, 1.49, which puts it in group 6 of 6, group 1 being the genes least tolerant of losing a copy. Missense variants: 188 observed, 214.53 expected, observed/expected ratio (o/e) 0.88, 90% interval 0.78 to 0.99. Synonymous variants: 79 observed, 80 expected, observed/expected ratio (o/e) 0.99, 90% interval 0.82 to 1.19.
Homologues: Orthologues: chimpanzee CFAP276 (99% identical), dog CFAP276 (85% identical), pig CFAP276 (85% identical), macaque CFAP276 (83% identical), rabbit CFAP276 (82% identical), guinea pig CFAP276 (77% identical), mouse Cfap276 (70% identical), rat Cfap276 (68% identical), zebrafish si:ch211-163l21.7 (43% identical), tropical clawed frog cfap276 (38% identical). Paralogues in human: FLVCR1 (23% identical), FLVCR2 (21% identical), SLC49A4 (17% identical), SLC49A3 (15% identical).
Diseases named in the same sentence as CFAP276 in open-access papers:
CFAP276 is named in the same sentence as 4 diseases in open-access papers, as found by Europe PMC text mining. Sharing a sentence is not in itself a finding about the gene and the disease.
CFAP276 shares sentences with these, for which no sentence is quoted: infertile (1 paper); Klinefelter syndrome (1); testicular diseases (1); tumour (1).